ACVR1 (activin A receptor type 1)
Diseases named in the same sentence as ACVR1 in open-access papers (continued):
Sharing a sentence is not in itself a finding about the gene and the disease.
glioma (16 papers, 1996 to 2025). A benign or malignant brain and spinal cord tumor that arises from glial cells (astrocytes, oligodendrocytes, ependymal cells). "Other studies support the increase in ID1 and ID2 expression levels in H3K27-altered gliomas, either through mutations in ACVR1 and the upregulation of pSMAD1/5 in H3.1-altered gliomas or through other mechanisms in H3.3-altered gliomas." (PMID 39126064, 2024). "Conversely, Activin A Receptor Type 1 (ACVR1), which is associated with mutations in H3.1K27M gliomas, is overexpressed in a subset of PFAs with poor outcome." (PMID 36759899, 2023). "Although the PDGFRA gene is amplified or mutated in some pediatric high-grade gliomas and DIPGs, these alterations are very rarely seen in ACVR1-mutant tumors." (PMID 32142668, 2020). "Consistent with this pattern, we identified high ACVR1—a gene frequently altered in H3.1-mutant DMGs—expression to be associated with: (a) worse survival in PFAs, and (b) upregulation of pathways that were also enriched in ACVR1-mutated gliomas." (PMID 36759899, 2023). "Other pHGG subtypes include those that are ACVR1-mutant, histone wild-type, such as pleomorphic xanthoastrocytoma (PXA)-like gliomas enriched with BRAF mutations, and NF1-associated gliomas with receptor tyrosine kinase fusions." (PMID 40647519, 2025). "E6201, a covalent MEK1/2 inhibitor, can inhibit ACVR1 and reduce growth of ACVR1 mutant glioma xenografts." (PMID 32142668, 2020). "In the subnetworks, several kinases, such as ABL1, ACVR1, EPHA4, MAPK9, PAK1 and SRC, were commonly associated with glioma, cell migration and cell death/survival." (PMID 32392905, 2020). "Immunohistochemistry staining of the glioma-like lesions demonstrated that cells within the lesions were proliferating and that a subset of cells expressed H3.1K27M and the mutant ACVR1." (PMID 30833574, 2019). "Overexpression of constitutively active ACVR1 induced apoptosis in glioma-initiating cells (GICs), while inhibition of ACVR1 reduced apoptosis of GICs." (PMID 31683698, 2019). "Next, the impact of panobinostat treatment on the growth and clonogenicity of human glioma cells, including the H3.3-K27M-mutant DIPG model HSJD-DIPG-007 that harbors H3.3-K27M and ACVR1-R206H mutations, was investigated." (PMID 28052119, 2017).
glioma (continued). "Thus, our findings add ACVR1 to NF1 deletion as an additional genetic alteration found in human gliomas that promote mesenchymal transformation." (PMID 30833574, 2019). "We noted that LDN212854 inhibited glioma neurosphere lines at a similar IC50s independent of expression of the ACVR1 R206H mutation." (PMID 30833574, 2019). "While the addition of PTEN loss led to the development of glioma-like lesions (6/10 = 60% for ACVR1 R206H and 6/15 = 40% for ACVR1 G328V), gliomagenesis did not occur." (PMID 30833574, 2019). "Importantly, the regional expression pattern of Pax3 is mirrored in human glioma, revealing a subset of BSG with high PAX3 expression that associates with alterations in PDGFRA and cell cycle regulatory genes and is exclusive of ACVR1 mutations." (PMID 25330836, 2014). "Overall, the mRNA levels of ACVR1, STAT3, WNT5A, KLF4 and DMC1 were obviously decreased in glioma samples with 1p19q codeletion compared to those in glioma samples without 1p19q codeletion." (PMID 36435765, 2022). "Importantly, Pax3 is regionally expressed in human glioma as well, with high PAX3 mRNA characterizing 40% of human BSG, revealing a subset of tumors that significantly associates with PDGFRA alterations, amplifications of cell cycle regulatory genes, and is exclusive of ACVR1 mutations." (PMID 25330836, 2014).
myeloma (15 papers, 2016 to 2025). "ACVR1 has been associated with multiple myeloma, a hematological cancer that arises from hematopoietic cells." (PMID 31683698, 2019). "It was described that BMP9 displayed tumour suppressor activity through ACVR1 signalling, inducing apoptosis and growth arrest in myeloma cells." (PMID 31683698, 2019). "Activin A has been shown to activate SMAD1/5/8 via ACVR1 in myeloma cell lines in the absence of ACVR1 mutation." (PMID 38672135, 2024). "In recent work, it was observed that activin A and B could signal through wild-type ACVR1 in myeloma cells, activating the SMAD1/5/8 signalling pathway and inducing myeloma cell death." (PMID 31683698, 2019). "The predominant receptor found in myeloma cells is ALK2, which is produced by ACVR1." (PMID 40136410, 2025). "The underlying mechanism of ActivinA/SMAD1/5 signaling is not fully understood but suggests ACVR1 dependency and independency of ACVR1B/C/TGFBR1 as demonstrated by inhibitor experiments in FOP iECs being in line with knockdown studies in FOP and myeloma cells." (PMID 33410098, 2021). "Furthermore, ACVR1/ALK2 is -in contrast to BMPRIA and -IB- ubiquitously expressed in myeloma cells, which potentially renders BMP6 a more versatile Activin A antagonist than BMP2." (PMID 28489849, 2017). "Therefore, it was proposed that a reduction in BMPR2 levels could increase ACVR1 complex formation with ACVR2A or ACVR2B, thus enhancing ACVR1-mediated SMAD1/5/8 signalling and myeloma cell death." (PMID 31683698, 2019).
ovarian carcinoma (11 papers, 2012 to 2025). A malignant neoplasm originating from the surface ovarian epithelium. "Given that AMH, BMPs, and ACVR1 modulate female fertility and ovarian function, ACVR1 has also been studied in ovarian cancer." (PMID 31683698, 2019). "In conclusion, while the main players in ovarian cancer are already known, further in-depth studies are needed to refine the relevance of ACVR1 in ovarian cancer." (PMID 31683698, 2019). "As explained in the reproductive system section, ACVR1 is one of the BMP type I receptors that binds AMH, which has been associated with ovarian cancer." (PMID 31683698, 2019). "This signal was found to induce proliferation of ovarian cancer cells through this ACVR1-SMAD signalling pathway." (PMID 31683698, 2019). "Our results support the idea that a panel of tumor-related proteins, including heterogeneously expressed proteins such as renin, ACVR1, TLR1, and KLKs,5,7,11 may encompass tumor heterogeneity in ovarian cancer patients." (PMID 34868557, 2021). "Altered BMP signalling in ovarian cancer was also observed in epithelial ovarian cancer cells since autocrine BMP9, which usually signals through ACVRL1, also signals through ACVR1, increasing the phosphorylation of SMAD1/5 and promoting ovarian cancer cell proliferation." (PMID 31683698, 2019).
breast carcinoma (10 papers, 2011 to 2025). "Besides, association of genetic variants in ACVR1 has been reported in breast cancer, and with anti-Mullerian hormone level in women having polycystic ovary syndrome." (PMID 32641001, 2020). "The functional relationship between miR-384 and ACVR1 has been highlighted in breast cancer with studies providing evidence suggesting that miR-384 suppresses breast cancer progression by down-regulating ACVR1." (PMID 30819221, 2019). "ACVR1 and BMPR1A have each been previously associated with breast cancer." (PMID 30566622, 2019). "We have previously reported that all six BMP specific receptors (ACVR1, BMPR1A, BMPR1B, ACVR2A, ACVR2B, and BMPR2) are uniformly expressed among the breast cancer cell lines studied here." (PMID 22118688, 2011).
myelofibrosis (9 papers, 2021 to 2026). A partial or complete replacement of the bone marrow stroma by fibrous tissue. "Momelotinib and pacritinib are potent ACVR1 inhibitors that are preferable to treat cytopenic patients with myelofibrosis." (PMID 38201581, 2023). "ACVR1 induces and regulates expression of Sonic Hedgehog (Shh) besides affecting hepcidin expression and hemoglobin (Hb) levels in myelofibrosis (MF)." (PMID 38201581, 2023). "Momelotinib is a JAK1/JAK2/activin receptor type-1 (ACVR1) ATP-competitive inhibitor that is being investigated in patients with myelofibrosis who have failed previous jakinib therapy (NCT01969838)." (PMID 35056105, 2021). "Furthermore, we found that especially Momelotinib its important role as a JAK1/JAK2/ACVR1 inhibitor in alleviating myelofibrosis and anti‐inflammation, which may serve as a potential drug for COPD treatment." (PMID 38578019, 2024).
prostate carcinoma (9 papers, 2012 to 2025). A carcinoma that arises from epithelial cells of the prostate gland. "Prostate cancer has been associated with ACVR1 through endoglin, a TGFβ superfamily auxiliary receptor identified as a marker of tumour angiogenesis and neovascularisation." (PMID 31683698, 2019). "This hypothesis adds information to the endoglin roles observed in prostate cancer, yet the mechanistic process regulating endoglin-ACVR1 functions should still be defined." (PMID 31683698, 2019). "However, it has been reported that endoglin also interacts with and activates ACVR1, inhibiting prostate cancer cell migration." (PMID 31683698, 2019). "This dual role of ACVR1 in prostate cancer cell migration should be further confirmed to ascertain whether this mechanism is also present in different cancer types and ACVR1-related pathologies." (PMID 31683698, 2019). "On the contrary, ACVR1 could also phosphorylate endoglin, promoting prostate cancer cell migration." (PMID 31683698, 2019). "Of the 32 target hub genes, 4 were mapped to cell signalling pathways including ACVR1 and ACVR2B in TGF-beta signalling, CDKN1A and GSK3B in ErbB signalling (adj.P val = 0.016) and CDKN1A and GSK3B genes in Prostate cancer pathways (adj." (PMID 36468011, 2022).
brain tumor (6 papers, 2015 to 2021). "A new understanding of the epigenetic and genetic causes of paediatric brain tumours has recently emerged revealing potential novel targets for drug development, including the growth factor receptor ALK2, encoded by the gene ACVR1." (PMID 31551357, 2019).
brainstem glioma (6 papers, 2019 to 2022). "Somatic mutations in ACVR1 have been associated with high-grade pediatric brainstem gliomas, but their specific role remains to be elucidated." (PMID 35888045, 2022). "Approximately 25% of childhood brainstem gliomas harbor somatic mutations in Activin A receptor type I (ACVR1) which encode the type I BMP receptor ALK2, inducing BMP pathway activation." (PMID 33790740, 2021). "We have developed a genetically engineered brainstem glioma model harboring the recurrent DIPG mutation, activin A receptor type I (ACVR1)-G328V (mACVR1) using the sleeping beauty transposon system." (PMID 33400737, 2020).
Splenomegaly (6 papers, 2022 to 2026). Abnormal increased size of the spleen. "Pacritinib is a JAK1-sparing inhibitor of JAK2/FLT3/IRAK1/activin A receptor type 1 (ACVR1) that has received accelerated FDA approval for patients with splenomegaly and/or symptoms and severe thrombocytopenia (platelet counts <50 × 109/L)." (PMID 37894394, 2023).
colorectal cancer (5 papers, 2014 to 2025). A primary or metastatic malignant neoplasm that affects the colon or rectum. "ACVR1 inhibitors may hold therapeutic potential as treatment agents targeting the tumor stroma in colorectal cancer; however, BMPs regulate tissue homeostasis by acting on Lgr5+ stem cells in the intestinal epithelium." (PMID 40745121, 2025). "Previously, ACVR1 was identified in exosomes originating from MC/9 murine cells and SW480 human colorectal carcinoma cells." (PMID 24884710, 2014).
diffuse midline glioma (5 papers, 2018 to 2024). A diffuse glioma that arises from the midline structures of the central nervous system. "Although most preclinical studies of diffuse midline glioma target H3K27M-related mechanisms, ACVR1 mutations remain an important driver of tumorigenesis in more than 30% of H3K27M-mutant diffuse midline gliomas." (PMID 34771443, 2021). "Somatic ACVR1 mutations are nearly exclusively limited to H3K27M-mutant diffuse midline glioma, occurring on only 0.3% of all other tumor types." (PMID 34771443, 2021). "While patients with diffuse midline gliomas predominantly had the histone H3 K27M mutation, additional driver mutations, such as ACVR1 and PPM1D were noted in all of the patients that were analyzed with 500 gene panel testing." (PMID 34257334, 2021). "ACVR1 gene mutation was found within diffuse midline glioma that originated within the cervical spine but can also be see in other midline gliomas." (PMID 34257334, 2021). "Recent studies have identified activating mutations gene encoding Activin Receptor Type 1 (ACVR1) in a subset of diffuse midline gliomas." (PMID 29164272, 2018). "Up to 32% of H3K27M-mutant diffuse midline glioma cases have ACVR1 mutations." (PMID 34771443, 2021). "The third patient with diffuse midline glioma, H3 K27M-mutant, was also found to have PIK3CA mutation within a highly conserved helical domain, and an ACVR1 mutation within the kinase domain." (PMID 34257334, 2021).
glioblastoma (5 papers, 2019 to 2026). The most malignant astrocytic tumor (WHO grade IV). "To date, most identified ACVR1 mutations have been restricted to DIPGs with the exception of one reported case of a pediatric glioblastoma that arose in the spinal cord and harbored a G328E mutation." (PMID 30833574, 2019). "As Stat3 signaling has been previously implicated in the mesenchymal transformation of adult glioblastomas, we hypothesized that the upregulation of mesenchymal markers by ACVR1 R206H in the presence of H3.1K27M is at least in part due to the activation of Stat3 signaling." (PMID 30833574, 2019). "Overexpression of ACVR1 in glioblastoma nude mice models lead to impeded tumour growth and longer survival." (PMID 33354912, 2021). "ACVR1 was studied using primary grade IV adult glioblastoma cells to elucidate the importance of BMPs in glioblastoma progression." (PMID 31683698, 2019). "Overexpression of ACVR1 or DLX2 in primary grade IV glioblastoma cells orthotopically inoculated in nude mice resulted in impeded tumour growth and led to longer survival in vivo." (PMID 31683698, 2019). "Additionally, brainstem progenitors expressing ACVR1-R206H, with or without H3.1-K27M, showed increased markers for EMT and STAT3 signalling, which has been involved in mesenchymal transformation into glioblastomas." (PMID 31683698, 2019).
pancreatic cancer (5 papers, 2020 to 2024). "While AFAP1-AS1 inhibition reduced its capacity to bind to miR-384 in a competitive manner, it increased miR-384 expression and downregulated ACVR1, thereby slowing the growth of pancreatic cancer." (PMID 39170516, 2024). "In pancreatic cancer tissues, there was a high expression of actin filament-associated protein 1 antisense RNA 1 (AFAP1-AS1) and activin receptor A type I (ACVR1), but a low expression of miR-384." (PMID 39170516, 2024). "In pancreatic cancer, ACVR1 was found to regulate the stem cells and tumorigenicity of pancreatic cancer cells." (PMID 34725559, 2021).
Astrocytomas (4 papers, 2014 to 2024). "K27M-H3.1 and ACVR1 mutations as well as ALT phenotype were only found in WHO grade III–IV astrocytomas, while PIK3CA mutations and PDGFRA gains/amplifications were found in WHO grade II–IV astrocytomas." (PMID 25047029, 2014).
leukemia (4 papers, 2007 to 2025). A malignant (clonal) hematologic disorder, involving hematopoietic stem cells and characterized by the presence of primitive or atypical myeloid or lymphoid cells in the bone marrow and the blood. "Indeed, the BMP inhibitor DM was first identified by its dorsalising effects in embryonic zebrafish, and analogues of DM that can target Acvr1 are now repurposed (from being a leukaemia therapy) and in clinical trials to prevent the ectopic mineralisation seen in FOP." (PMID 33668680, 2021).
melanoma (4 papers, 2012 to 2022). A malignant, usually aggressive tumor composed of atypical, neoplastic melanocytes. "This analysis identified activating SOS1 mutations associated with Noonan syndrome as significantly altered in melanoma and the first kinase-activating mutations in ACVR1 associated with adult tumors." (PMID 27304678, 2016).
Osteochondroma (4 papers, 2018 to 2022). A common, benign cartiliginous neoplasm arising from the metaphysis of bone. "Second, while palovarotene reduced severity of whole-body HO and inhibited osteochondroma formation in Pdgfrα-R206H mice, palovarotene treatment of Acvr1[R206H]FlEx/+;Prrx1-Cre mice resulted in more marked reductions in HO." (PMID 30226468, 2018). "Surprisingly, although benign osteochondromas have been reported in the majority of FOP patients 140, lack of oncogenic predisposition in FOP patients with identical mutations in ACVR1 suggests that the mutant ACVR1 favors tumor development initiated by Histone H3 disruptions." (PMID 30246251, 2019). "Under the NCGSD group 29, only models of osteochondromas (EXT2 type) and fibrodysplasia ossificans progressiva (FOP) (ACVR1 gene) have been investigated in zebrafish." (PMID 34490030, 2021).
endometrial cancer (3 papers, 2019 to 2025). Primary or metastatic malignant neoplasm involving the endometrium (mucous membrane that lines the endometrial cavity). "It should also be noted that mutations in the ACVR1 gene are observed in other types of cancers, including endometrial cancer, although the frequencies of the ACVR1 mutations are lower than those in DIPG." (PMID 35693928, 2022). "A recent bioinformatic analysis using the mutational data generated by The Cancer Genome Atlas (TCGA) consortium revealed that 3.3% of the endometrial cancer cohort carried ACVR1 mutations." (PMID 31683698, 2019). "In addition, mutations in ACVR1, the gene encoding ALK2, are more frequently observed in endometrial cancer (>6%) than in most other cancers." (PMID 35693928, 2022).